MIR5703 (microRNA 5703)
Synonyms: hsa-mir-5703; mir-5703
Gene: MicroRNA gene on chromosome 2 (227,472,132 to 227,472,187, forward strand). Ensembl gene ENSG00000284092.
Homologues: Orthologues: chimpanzee MIR5703 (98% identical).